SIRT3 (sirtuin 3)
Diseases named in the same sentence as SIRT3 in open-access papers (continued):
Sharing a sentence is not in itself a finding about the gene and the disease.
tumor (continued). "Increasing evidence closely relate SIRT3 to clinical outcomes of CRC, acting as a tumor promoter or suppressor." (PMID 38811901, 2024). "Among the sirtuins, SIRT1, SIRT3, SIRT4, and SIRT6 have been identified as significant targets for anti-tumor treatments; SIRT4 has been proposed as a tumor-suppressor protein, reducing glutamine entry into mitochondria in response to DNA damage." (PMID 39195514, 2024). "Studies have shown that the expression of SIRT2, SIRT3, SIRT6, and SIRT7 is increased in tumor-stage 1-4 subgroups, SIRT1 expression is increased in tumor-stage 1, and the expression of SIRT4 is decreased." (PMID 37096064, 2023). "Sirtuins, a family of orthologues of yeast silent information regulator 3 (SIRT3), 4 (SIRT4) and 5 (SIRT5) are important tumor suppressor genes located in mitochondria." (PMID 36809279, 2023). "The dysfunction or genetic abnormalities in mitochondrial tumor-suppressor proteins such as SIRT3 and MTUS1 lead to disturbances in mitochondrial energy metabolism, triggering cellular transformation and tumor development." (PMID 37627097, 2023). "The high expression of PD-L1 in tumor cells promotes lymph node metastasis and enhances glucose metabolism in tumor cells through the SNAI1/SIRT3 pathway, but PD-L1 has the opposite effect on T-cell glycolysis." (PMID 37342333, 2023). "With its selectivity established, the researchers explored the influence of SIRT3 on both short- and long-term effects of compound 117c in the MDA-MB-231 cell line, confirming a concentration- and time-dependent inhibition of tumor cell proliferation." (PMID 37765074, 2023). "Cancer cells have different metabolic patterns from normal cells, and SIRT3-mediated metabolism reprogramming could be critical in the cancer context, which is closely related to the mechanism of metabolism reprogramming, metastasis, and chemoresistance in tumor cells." (PMID 35832551, 2022). "Targeting the SIRT3/mito-COX-2/p-Drp1Ser616 signaling axis promoted MQC-dependent chemosensitivity via multi-pattern, anti-tumor mechanisms in HCC." (PMID 35159089, 2022). "H. pylori oncoprotein CagA downregulates sirtuin 3 (SIRT3), a tumor-suppressor protein that suppresses ROS production." (PMID 35681691, 2022). "To further demonstrate the role of SIRT3 in the modification of COX-2 deacetylation in vivo, we tested the effect of RSV on mito-COX-2 deacetylation and the resulting anti-tumor sensitivity to cDDP in the HepG2 cell xenograft-harboring nude mice model." (PMID 35159089, 2022). "Knocking-out SIRT3 makes Nf1−/− cells insensitive to the antineoplastic effect of NDI1, in line with an inhibitory effect on tumor growth of NDI1 that requires SIRT3 activity." (PMID 35393510, 2022). "In recent years, it has also been found that SIRT-3 can inhibit protein kinase B-dependent mitochondrial metabolism and EMT and play an anti-tumor role." (PMID 35906622, 2022). "Previous studies have shown that SIRT-3 can mediate metabolic reprogramming by down-regulating HIF-1 through deacetylation, thus reducing glycolysis rate to inhibit the Warburg effect in tumor cells." (PMID 35906622, 2022). "Furthermore, SIRT3 may also inhibit tumor growth and metastasis." (PMID 35571098, 2022). "However, it is controversial whether SIRT3 acts as an oncogene or a tumor suppressor in CLL." (PMID 36230534, 2022). "Another significant consequence of Sirt3-mediated inhibition of ROS production is the downregulation of hypoxia inducible factor 1 (HIF1), which plays a key role in the regulation of tumor cell metabolism." (PMID 35938164, 2022). "SIRT3, a nicotinamide adenine dinucleotide- (NAD-) dependent deacetylase, was often recognized as a tumor-suppressor gene." (PMID 35136826, 2022). "Moreover, the SIRT3 function can vary between tumor types and may even oppose." (PMID 34747319, 2022).
tumor (continued). "SIRT3 also functions as a tumor suppressor in HCC through the PI3K/Akt pathway, where downregulation of SIRT3 and mitochondrial protein hyperacetylation increased cell proliferation and migration/invasion in HCC." (PMID 35805129, 2022). "Decreased SIRT3 was found to decrease IDH2 and SOD2 hyperacetylation by increasing the level of reactive oxygen species, suggesting that SIRT3 acts as a tumor suppressor in B cell malignancies." (PMID 36230534, 2022). "The UPRmt axis, including SIRT3, PERK, CHOP, ATF4/5, ETC pathways, mainly aggravates the tumor progression." (PMID 34717757, 2021). "SIRT3, a master regulator of mitochondrial metabolism, suppresses HIF-1α and tumor growth by inhibiting mitochondrial ROS production from complex III." (PMID 34829708, 2021). "The upregulation of the HSP60, HSP10, SIRT3, and hindrance of CHOP pathway due to UPRmt of the tumor cells enhances the chemoresistance, aggressive growth, and hindered biogenetic pathway inside the tumor cells." (PMID 34717757, 2021). "Intriguingly, in CRC, SIRT3 displays an oncogenic role by deacetylating SHMT2, and acts as tumor suppressor by increasing ROS production and PINK1/Parkin/mitophagy axis activation." (PMID 34680344, 2021). "The expression levels of SIRT3 and SIRT7 were correlated with high Ki-67 expression, i.e., a high proliferation rate, in GCT samples, implying roles in tumor cell proliferation." (PMID 33669567, 2021). "To enhance the anti-tumor effect of sorafenib, we employed PD0332991 (CDK4/6-Rb inhibitor) based on the correlation between SIRT3 and phosphorylated retinoblastoma protein in HCC." (PMID 32306906, 2020). "Conversely, SIRT3 and SIRT6 also act as tumor suppressors, restricting aerobic glycolysis in cancer cells through destabilization of hypoxia inducible factor 1 subunit alpha (HIF-1α) and inhibition of glycolytic kinases, respectively." (PMID 33117804, 2020). "The expression levels of SIRT1, SIRT3, SIRT5, SIRT6, and SIRT7 were significantly correlated with tumor stage and histological grade." (PMID 32158696, 2020). "In our study, we revealed that MTHFD2 is a novel substrates of SIRT3, which results in keep MTHFD2 enzyme activity and NADPH production in tumor cells." (PMID 32811824, 2020). "The deletion of SIRT2 and SIRT3 stimulated HIF-1α expression and activity, thereby promoting Glut1 expression, glucose uptake and tumor growth." (PMID 31849939, 2019). "The expression of the mitochondrial SIRT3 is consistently reported to be downregulated in HCC samples, where its decreased expression correlates with reduced overall survival, tumor progression and recurrence." (PMID 31060333, 2019). "pylori-infected SIRT3-overexpressing cells, indicating that SIRT3 is an effector molecule responsible for negative regulation of ROS, HIF-1α, and tumor growth induced by H. pylori CagA." (PMID 29108235, 2017). "To demonstrate the role of SIRT3 in the progression of tumors, we injected control and SIRT3 knockdown AGS cells into the flanks of nude mice, and tumor growth was measured after the subcutaneous injection." (PMID 29108235, 2017). "All of these findings suggest a novel mechanism whereby downregulation of SIRT3 in H. pylori CagA+ infected gastric cells induces ROS, HIF-1α activity, and tumor growth." (PMID 29108235, 2017). "SIRT3 and SIRT4 are tumor suppressor genes and the primary mitochondrial deacetylase which regulates metabolic function through variety of mechanisms." (PMID 26785117, 2016). "A family of orthologues of yeast silent information regulator 3 (SIRT3), 4 (SIRT4) and mitochondrial tumor suppressor 1 (MTUS1) are important mitochondrial tumor suppressor genes which play an important role in the progression of multiple cancers." (PMID 26785117, 2016).
tumor (continued). "Interestingly, SIRT3 expression in intestinal type of tumor tissues (15 cases; 93.3% strong positive and 6.6% weak positive) was significantly higher than that in diffuse type of tumor tissues (14 cases; 14.3% strong positive, 78.6% weak positive and 7.1% negative)." (PMID 26121691, 2015). "We also found that glycogen formation was significantly increased by SIRT3 overexpression (1.5-fold in AGS and 1.3-fold in SGC-7901), a feature of quick growth of tumor cell, while reduced by SIRT3 knockdown (40% in AGS and 70% in SGC-7901)." (PMID 26121691, 2015). "To further determine the role of SIRT3 in tumor formation ability, we injected SIRT3 overexpression and knockdown SGC-7901 cells into flanks of nude mice and tumor growth was allowed for 28 days after cell inoculation." (PMID 26121691, 2015). "The influences of OA on the protein expressions of HIF1α, SIRT3, and SOD2 in tumor tissue of the nude mice inoculated with MCF-7 cells were consistent with that inoculated with MDA-MB-231 cells." (PMID 25855962, 2015). "Among them was SIRT3, a sirtuin with NAD-dependent deacetylase activity, which is a tumor suppressor that protects against carcinogenesis by maintaining mitochondrial integrity and efficient oxidative metabolism." (PMID 25103363, 2014). "Significant correlations were found between SIRT3 expression and variables including differentiation (P = 0.013), clinical stage (P = 0.005), serum AFP level (P<0.01), tumor multiplicity (P = 0.026) and relapse (P = 0.028)." (PMID 23272146, 2012). "Results indicated that SIRT3, as well as tumor size, serum AFP level, tumor multiplicity, clinical stage, vascular invasion, tumor differentiation, and relapse, was responsible for outcome of HCC patient who underwent surgical resection." (PMID 23272146, 2012). "We next further confirmed the reverse connection of SIRT3 expression in HCC and tumor differentiation." (PMID 23272146, 2012). "Collectively, these findings support SIRT3 as a functionally tumor-suppressive mitochondrial regulator in NSCLC and suggest that OA-OEt may represent a promising SIRT3-activating lead compound." (PMID 42212315, 2026). "In NHL and HCC, SIRT3 deacetylates and activates GSK‐3β, inducing the expression and mitochondrial translocation of the proapoptotic protein Bax and triggering mitochondrial apoptosis, thereby inhibiting tumour growth." (PMID 39778006, 2025). "SIRT3 deacetylates IDH2 at K413, which activates its enzymatic activity by promoting IDH2 dimer formation, subsequently reducing intracellular ROS and glycolysis, and inhibiting the tumour‐prone phenotype." (PMID 39778006, 2025). "This difference suggests that while SIRT3 may contribute to tumor aggressiveness, SIRT5 may help protect against tumor development." (PMID 40710366, 2025). "The research group led by Liu Guangwei from the School of Life Sciences at Beijing Normal University has found that the NAD+- dependent deacetylase SIRT3 in mitochondria can regulate the differentiation and function of TFH cells, and play a key regulatory role in anti-tumor immunity." (PMID 40027134, 2025). "The RNA-seq analysis revealed that SIRT3 is lowlier expressed in ESCC tumor tissues than that in normal tissues, indicating that SIRT3 expression is negatively correlated with the development of ESCC." (PMID 40252727, 2025). "SIRT2 and SIRT3 have been reported to inhibit tumor progression by de-lactylating non-histone proteins." (PMID 39979245, 2025). "SIRT3 (sirtuin-3), an NAD+-dependent deacetylase, is a member of the sirtuin family residing in mitochondria and acting as a key regulator of metabolic reprogramming, DNA damage repair, and cell death in normal and tumor cells." (PMID 40777993, 2025). "However, due to the inability of HPNE-KRAS cells to form tumor in mice, we were unable to use HPNE cells to test the functional roles of RCC1 and SIRT3 in vivo." (PMID 41391757, 2025).
tumor (continued). "It has recently been discovered that SLC25A51 could sustain mitochondria acetylation homeostasis and proline biogenesis by promoting the deacetylation function of Sirtuin 3 (SIRT3), which may ultimately prompt the proliferative capacity of tumor cells." (PMID 38966636, 2024). "The absence of SIRT3 correlates with a glycolytic shift, offering a targetable axis to manipulate tumor metabolism." (PMID 38542426, 2024). "Furthermore, we used the Ualcan website to examine the expression of SIRT3 in NSCLC tissues, and the analysis results identified SIRT3 expression was lower in NSCLC with higher tumor histological stage." (PMID 39501597, 2024). "However, NMRGs with significant AUC values (AOX1, SIRT3, NMRK1, PARP1) were differentially expressed among tumor stages." (PMID 38254798, 2024). "The complexity of SIRT3 function is further magnified by its involvement in various regulated cell death (RCD) pathways, where it has been shown to exhibit both tumor-suppressive and tumor-promoting effects." (PMID 38773972, 2024). "The stabilization of Hif-1α in the absence of Sirt-3 has been described previously and is mostly considered in the context of the tumor microenvironment and the Warburg effect." (PMID 38612678, 2024). "Additionally, SIRT3 has been reported to play a dual role in cancer by affecting EMT and tumor immune response." (PMID 38773972, 2024). "While SIRT3 deacetylates mitochondrial metalloprotease YME1L1 to promote mitochondrial fusion and OXPHOS, thereby facilitating T cell infiltration into tumor tissue and enhancing anti-tumor immunity." (PMID 38773972, 2024). "At the same time, we analyzed the correlations between individual gene and pathway score using the spearman method and detected a negatively linear correlation between the pathway scores and SIRT3 expression in NSCLC, such as G2M checkpoint and tumor proliferation." (PMID 39501597, 2024). "The tumor suppression ability has also been reported for SIRT2 and SIRT3." (PMID 36769283, 2023). "Our results based on the clinical-pathological characteristics of patients with ccRCC showed that the expression of SIRT2, SIRT3, SIRT6, and SIRT7 was increased in tumor-stage 1-4 subgroups, SIRT1 was increased in tumor-stage 1, and the expression of SIRT4 and SIRT5was decreased." (PMID 37096064, 2023). "SIRT3 overexpression does not further decrease tumor growth in a TRAP1-null background, whereas NIC treatment almost abrogates it." (PMID 35393510, 2022). "Accordingly, the antineoplastic effect of both SIRT3 overexpression and NIC administration is higher in TRAP1 knock-out cells, suggesting that targeting multiple metabolic components can dramatically hit tumor growth." (PMID 35393510, 2022). "Targeting the suppression of mito-COX-2 and selective induction of SIRT3 could inhibit p-Drp1Ser616-driven mitochondrial fission, to induce apoptosis and sensitize HCC cells to multipattern anti-tumor therapy." (PMID 35159089, 2022). "Like SIRT3, studies have shown that SIRT5 can play a tumor-promoting or tumor-suppressing role." (PMID 36117172, 2022). "Accumulating evidence has suggested that SIRT3 and SIRT6 could be served as the tumor suppressors, thus, the abnormal sirtuin status might be also responsible for the different clinical outcomes among three ECM-based clusters." (PMID 36311789, 2022). "Thus, in prostate cancer, Sirt3 inhibits RIPK3-mediated necroptosis and the innate immune response, promoting tumor progression." (PMID 35938164, 2022). "SIRT3 regulates cell metabolism reprogramming, such as TCA, OXPHOS, and FA metabolism, to maintain mitochondria homeostasis, thereby affecting the fitness and survival of tumor cells." (PMID 35832551, 2022). "The authors speculated that in patients with B-ALL relapse, SIRT3 and NADSYN1 were up-regulated in response to certain tumor factors." (PMID 36439178, 2022). "This study suggested that SIRT3 and SIRT6 promote tumor progression." (PMID 35571098, 2022).
tumor (continued). "It is therefore plausible that TBX2 could reposition SIRT3 to reduce promoter-specific and/or global H4K16 acetylation, a phenomenon which has been reported in multiple tumour types." (PMID 35687133, 2022). "The effects of SIRT3 and CDT1 were determined in the nude mice xenografted with the tumor." (PMID 33655712, 2021). "However, another study showed that SIRT1, SIRT3, and SIRT6 function as the tumor suppressors in RCC." (PMID 34778292, 2021). "Among the seven SIRTs, SIRT1, SIRT3, and SIRT6 can be used as tumor suppressors in KIRC." (PMID 34194607, 2021). "In mammals, Sirt3 functions as a tumor suppressor, and mice lacking Sirt3 are more prone to cancer development." (PMID 34190584, 2021). "By immunohistochemical staining of Sirt3, p-ATM, p-Chk2 and γ-H2AX in each group of tumor tissues, it was also found that the activation of γ-H2AX was more pronounced in Sirt3 knockdown group, and the radiation-induced activation of p-ATM was significantly attenuated." (PMID 34405009, 2021). "Furthermore, SIRT3 knockdown in DLBCL cells and mice significantly impaired cell proliferation and tumor growth." (PMID 34650436, 2021). "Moreover, SIRT3/SOD2 signaling pathway has been shown to be involved in integrin-induced ROS generation in platelets and tumor cells." (PMID 34616362, 2021). "Most tumor samples with highly expressed MTHFD2 exhibited the upregulated protein levels of SIRT3 compared with adjacent nontumor tissues (P < 0.01)." (PMID 32811824, 2020). "We demonstrated that Rapha Myr® influences most of the sirtuins except the mitochondrial SIRT3, considered an EMT-repressor and tumor-suppressor protein principally regulating oxidative response, energetic balance, and cellular metabolism, thus promoting genomic and mitochondrial DNA instability." (PMID 32727075, 2020). "In conclusion, down-regulation of expression of certain mitochondrial tumor-suppressor genes, such as SIRT3, SIRT4, and MTUS1, in HNSCC cells indicates aggressive tumor behaviors, and may predict an unfavorable clinical outcome." (PMID 33585187, 2020). "However, SIRT3 was reported to be up-regulated in the mitochondrial fraction of human RCC tissues, and knockdown of SIRT3 inhibited RCC cell proliferation and tumor growth in vivo." (PMID 32158696, 2020). "So far, it has not been shown that Sirt3 exerts its tumor-suppressive function in MCF-7 cells by interfering with their response to E2." (PMID 32244715, 2020). "More intriguingly, activation of SIRT3 by Honokiol can protect against doxorubicin-induced cardiotoxicity in tumor-xenograft mice without affecting the anti-tumor effect of doxorubicin." (PMID 32724473, 2020). "Tumors in mice lacking Sirt3, which contain MnSOD-Ac, display a luminal B-like tumor signature, including increased Ki-675." (PMID 31160585, 2019). "The median SIRT-3, p-mTOR and nuclear HIF-1α expression levels (percent of immunopositive tumor cells) were 35 (IQR 10–60), 0 (IQR 0–0) and 1 (IQR 0–10) in early-stage patients vs. 60 (IQR 10–90), 0 (IQR 0–0) and 0 (IQR 0–7.5) in advanced-stage patients, respectively." (PMID 30917505, 2019). "The expression levels of SIRT3 were lower in the cancer patient tissues but higher in normal tissues, while the expression levels of STAT3, HIF‐1α, GLUT1, LDHA, and HK2 were higher in tumor tissues but lower in normal tissues." (PMID 30094960, 2018). "Here, we show that HKL-mediated activation of SIRT3 also protects the heart from doxorubicin-induced cardiac damage without compromising the tumor killing potential of doxorubicin." (PMID 28423723, 2017). "Low SIRT3 expression and subsequent hyperacetylation and inactivation of SOD2 are thought to play a major role in the O2•−-driven activation of HIF-1α, leading to increased glycolysis in tumor cells." (PMID 29099803, 2017).